INS (insulin)
Diseases named in the same sentence as INS in open-access papers (continued):
Sharing a sentence is not in itself a finding about the gene and the disease.
tumor (continued). "Additionally, insulin promotes cell proliferation and increased insulin, in addition to insulin-like growth factor 1 (IGF1) and IGF2 levels, critically stimulates tumour initiation and progression in insulin-resistant patients." (PMID 37761999, 2023). "Interestingly, both events were strongly influenced by glucose levels and insulin stimulation, suggesting a critical role of glucose metabolism in both tumor cells." (PMID 37361518, 2023). "Moreover, it was shown that key circadian rhythm hormones (melatonin, testosterone and glucocorticoids) dictate the generation dynamics of CTCs, and insulin directly promotes tumour cell proliferation in a time-dependent manner." (PMID 37238992, 2023). "Since tumour‐specific ImpL2 inhibition significantly rescued muscle translation, we suspected that insulin signalling in the muscle may play a role in modulating muscle integrity." (PMID 38014610, 2023). "Limiting glucose availability for tumours by adapting into ketosis may therefore create a metabolically unfavourable environment for tumour growth, whilst also reducing insulin and IGF-1′s growth and division stimulating signals." (PMID 37958602, 2023). "Although cellular senescence is a defensive mechanism that inhibits tumor growth, when it occurs in adipose tissue, it results in impaired adipogenesis, inflammation, abnormal adipocytokine secretion, and insulin resistance, all of which contribute to adipose dysfunction." (PMID 37794966, 2023). "Moreover, the effects of adiponectin on tumor tissues are mediated by various intracellular pathways, modulation of tumor angiogenesis, insulin sensitivity, and inflammation." (PMID 37763777, 2023). "Among the hypotheses mentioned, the tumor itself may produce substances that increase resistance to insulin in muscle and adipose tissues." (PMID 37697301, 2023). "Because tumor cells and stem cells have highly similar biological characteristics, we hypothesized that insulin may inhibit proliferation and induce differentiation of tumor cells." (PMID 37058027, 2023). "And SAT produces leptin and maintains insulin sensitivity, thus impairing tumor progression." (PMID 37980639, 2023). "Broadly, metformin is currently a typical example of a non-oncology anticancer drug, driven by the hypothesis of reducing the availability of glucose and insulin to slow down the tumor growth and progression." (PMID 37274234, 2023). "The excessive insulin secretion by the tumour leads to repeated episodes of hypoglycaemia." (PMID 37894845, 2023). "Thus, insulin signaling interacts with active Notch to promote primary and allograft tumor growth at early and progressed stages." (PMID 37549261, 2023). "Additionally, metformin can inhibit insulin-mediated tumor growth by lowering systemic insulin levels." (PMID 37278858, 2023). "In previous publications, we tried to explain the metabolic rewiring of tumor cells by considering that tumor cells respond to both anabolic insulin and to catabolic glucagon, since enzymes such as PK and PDH remain phosphorylated, as for glucagon-mediated neoglucogenesis." (PMID 36836124, 2023). "Most clinicians expect peripheral neuropathy symptoms to reverse completely after the insulin-secreting tumor is resected, but this may be a misassumption." (PMID 37308982, 2023). "However, insulin supplementation was able to attenuate tumor‐mediated effects on the cardiac tissue." (PMID 37654192, 2023). "Therefore, the availability of glucose in the vicinity of the tumor cells, as well as the presence of insulin, leads to increased tumor progression." (PMID 37511575, 2023). "In colon cells cultured as spheroid and enriched in CSCs, insulin increased PD-L1 expression and transport to the cell membrane through the PI3K/Akt pathway, thereby suggesting that PD-L1 expression in colon CSCs is dynamic and responsive to insulin in the tumor environment." (PMID 36672737, 2023).
tumor (continued). "The most important and well-defined of them include the metabolic profile of hormones, the systemic inflammation reduction, the insulin sensitivity increase, the antioxidant capacity augmentation, the boost to the immune system, and the direct effect on the tumor." (PMID 37958310, 2023). "In addition, raised plasma insulin levels and insulin-like growth factor-1, both known to promote tumor growth." (PMID 37468880, 2023). "As TGF‐β signalling acts downstream of insulin signalling in the fat body of tumour bearing animals, we next asked if inhibition of TGF‐β signalling in the fat body via the expression of an RNAi against mad improved muscle atrophy in tumour bearing animals (QRasV12ScribRNAi)." (PMID 38014610, 2023). "The pro-tumoural effects of leptin are facilitated by its mitogen actions and leptin acts directly on tumour growth, migration and invasion signalling pathways or affects tissue insulin sensitivity, inflammatory responses and tumour angiogenesis to exert neoplastic effects in breast cancer." (PMID 37620316, 2023). "This will allow a more comprehensive examination of whether known sex differences in the regulation and physiological action of insulin in the body contribute to tumor development." (PMID 35189981, 2022). "Moreover, insulin also directly influences tumor development through promotional and antiapoptotic effects." (PMID 35207622, 2022). "In addition, an HCC mouse trial showed a positive correlation between tumor load and post-prandial serum insulin levels." (PMID 35600387, 2022). "In conclusion, this study demonstrated a novel approach, combining the radiosen-sitizing properties of GNPs together with the BBB-crossing properties of insulin and the tumor-targeting properties of CTX, which effectively improved treatment outcomes in mice carrying intracranial glioblastoma." (PMID 36324626, 2022). "Another explanation is the hypothesis that animal fat intake increases the synthesis of estrogens from androstenedione and insulin levels, i.e., compounds that promote tumor growth." (PMID 35406496, 2022). "In addition to improving metabolism and stimulating the growth and proliferation of normal and tumour cells, insulin can promote RNA and DNA synthesis in cells and tissues and induce tumour cell proliferation." (PMID 36776356, 2022). "In addition, IGF-1 appears to play a role in tumour initiation and development in insulin-resistant patients." (PMID 36290362, 2022). "Our data indicate that increased leptin levels but not insulin, is associated to increased tumor growth." (PMID 35361802, 2022). "The activation of the AMPK-pathway may reduce the activity of insulin in promoting tumor progression and can inhibit the mammalian target of rapamycin (mTOR), which is closely connected to tumor cell proliferation." (PMID 36280839, 2022). "Serum levels of IGF-1 and insulin were also assessed at tumour endpoint." (PMID 35908046, 2022). "However, compared to pre-tumour endpoint, insulin levels were reduced at tumour endpoint in the HFD group likely reflecting long term HFD induced pancreatic beta cell dysfunction." (PMID 35908046, 2022). "Insulin-tolerance and glucose-tolerance tests showed a marked improvement of insulin sensitivity and quick glucose clearance under cold exposure in the xenograft and spontaneous tumour models." (PMID 35922508, 2022). "Indeed, insulin producing cells were drastically reduced in islets in tumor-free KPC7−/− animals compared to islets in tumor-free tissue regions adjacent to PDACs in KPC and KPC7−/− mice." (PMID 35372352, 2022). "Indeed, their impact is important on the factors that control the tumor development, such as the immune system, inflammation, tissue perfusion, hypoxia, insulin resistance, the amount of lactates, metabolism, glucocorticoid levels and cachexia." (PMID 36358820, 2022).
tumor (continued). "We considered that FABP4 may be involved in regulation of tumour-associated macrophage function, lipid droplet catabolism, fatty acid metabolism for energy supply and insulin resistance, and may potentially influence tumour development and progression." (PMID 36532833, 2022). "In this study, high-fat feeding induced serum insulin levels, but we did not observe any association between circulating insulin levels and regulation of tumor growth, which contrasts with previously published statements that insulin levels would promote tumor growth." (PMID 35361802, 2022). "Resistin is acknowledged as a novel secretory factor from adipocytes, and may regulate inflammatory responses, affect tumor angiogenesis and modulate insulin sensitivity." (PMID 35701840, 2022). "Factors released by adipocytes, represented by leptin, insulin, and IL-6, can domesticate macrophages toward the function of promoting tumor malignancy, manifested by the changes in the secretion profile of macrophages, including pro-angiogenic VEGF and pro-inflammatory IL-6." (PMID 35701840, 2022). "In addition, metformin indirectly inhibits tumor growth, proliferation, invasion and metastasis by reducing the concentration of glucose in the blood, insulin resistance, as well as by reducing inflammation and affecting the tumor microenvironment." (PMID 36337018, 2022). "In individuals with OA, the development of these diseases is favoured through pathophysiological mechanisms that lead to an increase in the inflammatory process, greater insulin resistance, mitochondrial dysfunction, and the secretion of adipokines that stimulate the proliferation of tumour cells." (PMID 36296999, 2022). "Differential effects of 4EBP1-4A on the translation of HK1 and HK2 suggest that 4EBP1 may regulate glucose and insulin metabolism to inhibit tumor growth, and this needs to be explored." (PMID 35626002, 2022). "Moreover, insulin increases the activity of insulin-like growth factor-1 involved in tumor initiation and progression." (PMID 35574372, 2022). "Supporting the theory that the amount of the retained normal pancreatic tissue is responsible for the dichotomy of the KPC7−/− cohort is the fact that the islets of Langerhans were unremarkable with ample insulin expressing cells in tumor-free tissue adjacent to tumors in KPC and KPC7−/− mice." (PMID 35372352, 2022). "Indeed, mouse tumor models show insulin feedback is induced by PI3K inhibitors, reactivating PI3K signaling, thus compromising their efficacy." (PMID 34759345, 2022). "More clinical evidence is needed to help form an expert consensus on whether insulin should be used cautiously in tumor patients receiving anti-PD1 antibody therapy." (PMID 36033393, 2022). "Tumors in Pb-Cre4;Ptenf/f mice may be less sensitive to insulin/tumor-extrinsic CAMKK2 functions since there is already high basal mTOR signaling." (PMID 35741020, 2022). "Furthermore, impairment of insulin signaling also promotes liver gluconeogenesis thereby enhancing tissue wasting and tumor progression." (PMID 35441960, 2022). "As for diabetic PDA patients, insulin is a definite tumor-promoting factor." (PMID 35252207, 2022). "Moreover, insulin also promotes tumor cell growth by altering the energy metabolism of tumor cells through the aberrant mTOR pathway to upregulate glucose uptake and glycogenolysis." (PMID 35933633, 2022). "As the main target organ of insulin, any pathological processes such as inflammation or neoplasia occur in the liver, will block the insulin signaling pathway and cause IR, which has been shown to be an independent risk factor accelerating the progression of HCC." (PMID 35281088, 2022). "It is known that mitogen-activated protein kinases (MAP4K1 and MAP4K4) and the insulin resistance pathway (PRKCD and PRKAB1) may be associated with tumor progression through modulation of gene expression responsible for cell cycle, proliferation, and growth." (PMID 35453789, 2022).
tumor (continued). "This suggests that dapagliflozin may slow 4T1 tumor growth primarily by its effect to lower circulating insulin concentrations." (PMID 35595952, 2022). "Insulin is a growth factor and it is possible that high levels of endogenous or administration of exogenous insulin could stimulate tumour growth." (PMID 35681699, 2022). "Moreover, adiponectin was deemed to be a strong inhibitor of the PI3K/Akt/mTOR pathway, thus limiting the tumor cell growth induced by insulin and by other growth factors." (PMID 35384390, 2022). "Adipocytes play an important role in tumor growth; they actually produce and secrete various adipokines to facilitate interorgan crosstalk and indirectly affect tumor cell biology by regulating insulin resistance and inflammation." (PMID 35207557, 2022). "Secondly, it may modulate the microbiota through short-chain fatty acids production, and improve glucose homeostasis and insulin sensitivity, both related to tumor proliferation and anti-inflammatory effects." (PMID 36558447, 2022). "Some other data of interest were also missing from hospital records (under-reporting), such as insulin and dietary assessment, which could provide insights into the interrelationship between diet, nutritional status, and tumor characteristics." (PMID 36432611, 2022). "Since HFD was shown to change metabolic programming of cancer cells in the tumor microenvironment and IF is known to decrease several metabolic parameters such as insulin and glucose, future studies should investigate how IF can impact tumor microenvironment metabolic programming." (PMID 35186923, 2022). "Glimepiride, pioglitazone, and insulin weaken the effect of anti-PD1 in tumor treatment." (PMID 36033393, 2022). "Current clinical guidelines recommend annual surveillance for tumours by biochemical analyses (e.g. calcium, fasting glucose and hormones such as insulin, gastrin and prolactin) and radiological examination including MRI (or CT) scans of the pancreas and pituitary." (PMID 35900839, 2022). "As demonstrated by experimental evidence, omentin-1 preserves body metabolism as well as enhances insulin sensitivity and exerts anti-inflammatory, anti-atherogenic, and tumor growth-regulating effects through AMPK, AKT, NF-κB, MAPK, ERK, JNK, and p38 signaling." (PMID 35875143, 2022). "Notably, tumours were less advanced in septic patients compared to control and insulin-resistant subjects." (PMID 35017615, 2022). "Dietary fiber may reduce pro-inflammatory cytokines in the tumor microenvironment; improve insulin sensitivity, lipid metabolism, and endothelial function; produce gastrointestinal butyrate which modulates the immune response." (PMID 34572881, 2021). "In addition, analysis of expression levels of TUNEL, Ki-67, and caspase-3 showed that co-administration of insulin with 5-FU significantly promoted tumor apoptosis and inhibited tumor proliferation compared with administration of 5-FU alone." (PMID 34034636, 2021). "We think that knocking out MMP12 in ApcMin/+ mice may lead to partly insulin degradation, and affect insulin sensitivity and the balance of glucose utilization induced by tumor growth." (PMID 34863141, 2021). "Tumor growth might be promoted by the direct action of insulin, as an anabolic factor and oncogene, or indirect action through IGF-1." (PMID 34208601, 2021). "Second, metformin can also reduce the activation of insulin/IGF-1 (insulin-like growth factor 1) receptors in tumor cells, resulting in reduced stimulation of the mitogenic pathway, thereby indirectly inhibiting cell proliferation, tumor formation and metastasis." (PMID 33976288, 2021). "Based on these findings, we believe that in Tu‐Sk.T6Tg mice, over‐expressed SIRT6 might have reduced tumour growth and associated muscle wasting via downregulation of secreted CXCL10 and preservation of plasma level of insulin." (PMID 34212132, 2021).
tumor (continued). "Furthermore, several studies suggest that leptin and ObR are overexpressed in tumor tissues, due to hypoxia and/or as a response to insulin, IgF-1 and/or to estradiol." (PMID 33644151, 2021). "MiR-320b expression in human granulosa-like tumor cells decreased after insulin treatment." (PMID 34413875, 2021). "Dietary alterations can lead to changes in SC function, influencing the availability of nutrients or regulating hormone levels, growth factors controlling tissue homeostasis and tumour initiation, signalling factors (e.g., insulin and insulin-growth factor), and epigenetic patterns." (PMID 35052515, 2021). "Metformin increases the receptor sensitivity to insulin and enhances peripheral glucose uptake by activating the AMPK pathway, which may reduce the action of insulin in promoting tumor growth." (PMID 34149406, 2021). "Similarly, in dogs high Ki-67, high pre-operative serum insulin concentration, low post-operative glucose concentration, large tumor size, and advanced TNM stage indicate shorter overall survival." (PMID 34794032, 2021). "TNFα has been identified as a proinflammatory cytokine that kills tumor cells and microorganisms, but it has also been suggested to lower insulin sensitivity through induction of inflammatory molecules such as MCP1 and IL-6 and through the reduction of adiponectin expression." (PMID 35050148, 2021). "If the role of Wg in supporting yki3S/A tumor growth is to oppose the effect caused by ImpL2 elevation via increasing insulin/IGF signaling, augmenting insulin/IGF signaling in yki3S/A cells should be sufficient to rescue the growth defect caused by wg depletion." (PMID 34078667, 2021). "Notably, in cells overexpressing IR-A, insulin strongly induced genes involved in tumor progression and immune evasion including chemokines and genes related to innate immunity." (PMID 34831367, 2021). "In terms of toxicity, the main concern for using potent PI3Kα inhibitors remains the induction of insulin feedback which could feed the tumours." (PMID 34033220, 2021). "Paralleling processes that have been observed during tumor development, high demand for insulin that is accompanied by inflammatory stress may enhance the generation of aberrant insulin polypeptides formed by nonstandard translational initiation." (PMID 33671312, 2021). "Growth of the tumor may therefore occur in response to insulin, glucose and both IGFs (reviewed in:)." (PMID 34208601, 2021). "We next tested whether insulin was acting directly on the Py230 tumor cells to stimulate proliferation." (PMID 33495474, 2021). "Insulin administration is shown to lower plasma FFA levels in cachectic tumour‐bearing rats." (PMID 34212132, 2021). "In the present study, we aimed to better characterize the tumor-promoting actions of the IR-A vis a vis the IR-B in TNBC cells in response to insulin, and identify IR-A-specific gene profiles, which might reveal novel therapeutic approaches." (PMID 34831367, 2021). "However, it is worth noting that although adiponectin is also secreted by adipocytes, it has an anti-tumor effect, and can cross-talk with other adipokines (such as leptin and estrogen) and insulin to play an anti-tumor effect together." (PMID 34485124, 2021). "Thus, in addition to confirming the well-known mechanistic roles of insulin in TOR activation and protein synthesis, these fly studies identified essential intracellular and inter-organ signaling networks that mediate insulin-induced tumor progression." (PMID 34240146, 2021). "We found that in vivo moderate over‐expression of SIRT6 in skeletal muscle not only inhibited myostatin expression in autocrine manner but also normalized insulin levels and downregulated secretion of non‐esterified free‐fatty acid in the plasma via paracrine signalling in tumour‐bearing mice." (PMID 34212132, 2021). "These pathways may be affected in a tumor-promoting as well as a tumor-suppressing way by either metformin treatment or insulin supplementation." (PMID 33690729, 2021).